MYOG (myogenin)
Description:
Acts as a transcriptional activator that promotes transcription of muscle-specific target genes and plays a role in muscle differentiation, cell cycle exit and muscle atrophy. Essential for the development of functional embryonic skeletal fiber muscle differentiation. However is dispensable for postnatal skeletal muscle growth; phosphorylation by CAMK2G inhibits its transcriptional activity in respons to muscle activity. Required for the recruitment of the FACT complex to muscle-specific promoter regions, thus promoting gene expression initiation. During terminal myoblast differentiation, plays a role as a strong activator of transcription at loci with an open chromatin structure previously initiated by MYOD1. Together with MYF5 and MYOD1, co-occupies muscle-specific gene promoter core regions during myogenesis. Also cooperates with myocyte-specific enhancer factor MEF2D and BRG1-dependent recruitment of SWI/SNF chromatin-remodeling enzymes to alter chromatin structure at myogenic late gene promoters. Facilitates cell cycle exit during terminal muscle differentiation through the up-regulation of miR-20a expression, which in turn represses genes involved in cell cycle progression. Binds to the E-box containing (E1) promoter region of the miR-20a gene. Also plays a role in preventing reversal of muscle cell differentiation. Contributes to the atrophy-related gene expression in adult denervated muscles. Induces fibroblasts to differentiate into myoblasts (By similarity).
Synonyms: bHLHc3; Myf-4; MYF4
Tractability: No criterion of Open Targets' tractability assessment is met for any kind of drug.
Gene: Protein-coding gene on chromosome 1 (203,083,129 to 203,086,013, reverse strand). Ensembl gene ENSG00000122180.
Subcellular location: Nucleus
Subcellular location (Human Protein Atlas): Nucleoplasm
Pathways (Reactome):
Chromatin organization: CHD1 and CHD2 subfamily
Developmental Biology: Myogenesis
Signal Transduction: TGFBR3 expression
Gene Ontology:
Molecular function: DNA-binding transcription activator activity, RNA polymerase II-specific; protein binding; RNA polymerase II transcription regulatory region sequence-specific DNA binding; sequence-specific DNA binding; sequence-specific double-stranded DNA binding; DNA-binding transcription activator activity; DNA-binding transcription factor activity; DNA-binding transcription factor activity, RNA polymerase II-specific; E-box binding; RNA polymerase II cis-regulatory region sequence-specific DNA binding; chromatin DNA binding; cis-regulatory region sequence-specific DNA binding; protein dimerization activity
Biological process: positive regulation of transcription by RNA polymerase II; cellular response to estradiol stimulus; muscle cell fate commitment; negative regulation of cell population proliferation; positive regulation of muscle atrophy; positive regulation of myoblast differentiation; positive regulation of myotube differentiation; positive regulation of skeletal muscle fiber development; regulation of cell cycle; regulation of myoblast fusion; regulation of skeletal muscle satellite cell proliferation; response to denervation involved in regulation of muscle adaptation; response to electrical stimulus involved in regulation of muscle adaptation; response to muscle activity involved in regulation of muscle adaptation; skeletal muscle cell differentiation; skeletal muscle tissue development; striated muscle atrophy; animal organ development; muscle cell differentiation; muscle organ development; regulation of DNA-templated transcription; tissue development
Cellular component: nucleoplasm; chromatin; nucleus; protein-DNA complex; RNA polymerase II transcription regulator complex; transcription regulator complex
Genetic constraint (gnomAD): Loss-of-function variants: 6 observed, 16.57 expected, observed/expected ratio (o/e) 0.36, 90% interval 0.2 to 0.71. The upper end of that interval is the gene's LOEUF score, 0.71, which puts it in group 2 of 6, group 1 being the genes least tolerant of losing a copy. Missense variants: 272 observed, 300.03 expected, observed/expected ratio (o/e) 0.91, 90% interval 0.82 to 1. Synonymous variants: 125 observed, 129.92 expected, observed/expected ratio (o/e) 0.96, 90% interval 0.83 to 1.12.
Homologues: Orthologues: chimpanzee MYOG (100% identical), macaque MYOG (99% identical), pig MYOG (97% identical), guinea pig MYOG (96% identical), rabbit MYOG (96% identical), mouse Myog (95% identical), rat Myog (94% identical), dog MYOG (93% identical), tropical clawed frog myog (62% identical), zebrafish myog (59% identical), Drosophila melanogaster nau (37% identical), Caenorhabditis elegans hlh-1 (32% identical). Paralogues in human: MYF6 (46% identical), MYF5 (39% identical), MYOD1 (37% identical).
Diseases named in the same sentence as MYOG in open-access papers:
MYOG is named in the same sentence as 129 diseases in open-access papers, as found by Europe PMC text mining. Sharing a sentence is not in itself a finding about the gene and the disease. The quoted sentences say what the papers report.
rhabdomyosarcoma (111 papers, 1991 to 2026). A rare aggressive malignant mesenchymal neoplasm arising from skeletal muscle. "If the patient is accompanied by heterologous sarcoma components, such as rhabdomyosarcoma components with positive expressions of Desmin, Myogenin, and MyoD1, the risk of recurrence may increase." (PMID 38783282, 2024). "Both cell lines demonstrated histological features, respectively, corresponding to the implanted embryonal or alveolar variants of rhabdomyosarcoma, including nests of small round blue cells with fibrovascular septae and positive MyoD1 and Myogenin immunochemistry." (PMID 21559211, 2011). "Immunohistochemical(IHC) staining confirmed diffuse positivity for skeletal muscle lineage markers(desmin, myogenin, MyoD1) in the tumor cells, thereby establishing a definitive diagnosis of rhabdomyosarcoma." (PMID 41783407, 2026). "Rhabdomyosarcoma expresses desmin, MyoD1, or myogenin due to skeletal muscle differentiation, whereas small cell carcinoma expresses CK and CgA with or without Syn." (PMID 40978053, 2025). "Rhabdomyosarcoma typically shows positive staining for myogenin, desmin, sarcomeric actin, and myoglobin, while it is usually negative for NKX2.2, CD99, CD45, cytokeratin (CK), S100, and neuron-specific enolase (NSE)." (PMID 40094002, 2025). "This can also mimic lymphoma (CD45+), poorly differentiated carcinoma (cytokeratin+), GIST (DOG1/CD117+), and rhabdomyosarcoma (desmin/myogenin+)." (PMID 41458270, 2025). "For example, lymphoma is typically positive for leukocyte common antigen (CD45), whereas rhabdomyosarcoma expresses desmin and myogenin." (PMID 40084340, 2025). "It was shown that in rhabdomyosarcoma, MEK inhibition with trametinib causes the loss of ERK2 at the MYOG promoter as well as the transcriptional delay of MYOG expression." (PMID 37190100, 2023). "We previously developed a suicide-therapy approach for rhabdomyosarcoma in which the promoter region of MYOG (highly expressed in rhabdomyosarcoma) was modified to enhance rhabdomyosarcoma-specificity." (PMID 36158201, 2022). "This is in accordance with a recent finding that oncogenic Ras inhibits the expression of myogenin in a rhabdomyosarcoma model." (PMID 34553752, 2022). "We identified Arp5 as an inhibitory binding protein for MyoD and MyoG in skeletal muscle and rhabdomyosarcoma (RMS) cells." (PMID 35348112, 2022). "Alveolar rhabdomyosarcoma is recognized by staining strongly for myogenin (>50% of tumor cell nuclei), either in its classical or solid variants." (PMID 36173721, 2022). "On IHC staining, the neoplastic cells in pleomorphic rhabdomyosarcoma show positive reactivity with myogenin, desmin, smooth muscle actin (SMA) and vimentin." (PMID 34034720, 2021). "MYOGENIN is constitutively expressed in rhabdomyosarcoma, but only transiently during myogenic differentiation in skeletal muscle, and so was selected for modification to enhance ARMS, but reduce skeletal muscle, expression." (PMID 32973362, 2021). "Positive staining for skeletal muscle differentiation markers such as myoD1 and myogenin along with cross-striation are distinctive findings in rhabdomyosarcoma." (PMID 34162402, 2021). "Rhabdomyosarcoma is a rare childhood soft tissue cancer whose cells resemble poorly differentiated skeletal muscle, expressing myogenic proteins including MYOGENIN." (PMID 32973362, 2021). "A major goal was to design a promoter specific for rhabdomyosarcoma cells over myogenic cells, and while we increased rhabdomyosarcoma specificity with our ∆MEF3/NF1 MYOGENIN promoter, there remains residual toxicity in myoblasts." (PMID 32973362, 2021). "Pleomorphic rhabdomyosarcoma shows at least focally an expression of skeletal muscle-specific markers, i.e., myoglobin, MyoD1, or myogenin, and lacks positivity for melanocytic markers." (PMID 31309284, 2020). "Epithelioid rhabdomyosarcomas are positive for specific markers of skeletal muscle differentiation (e.g., myogenin, MyoD1)." (PMID 32316685, 2020).
rhabdomyosarcoma (continued). "Clinical and radiologic features and immunohistochemistry help to differentiate these from UESL (MSA, myogenin, and MyoD1 positive in rhabdomyosarcoma)." (PMID 32204368, 2020). "Rhabdomyosarcomas show rhabdomyoblasts or alveolar architecture and are positive for myogenin and MyoD1." (PMID 32316685, 2020). "Our data reveal a hijacked enhancer network that disrupts the stepwise CR TF logic of normal skeletal muscle development (PAX3 to MYOD to MYOG), replacing it with an “infinite loop” enhancer logic that locks rhabdomyosarcoma in an undifferentiated stage." (PMID 32416589, 2020). "A hallmark of rhabdomyosarcoma is that tumors express early markers along the skeletal muscle lineage such as MYOD1, MYOG and Desmin; however, these tumors fail to terminally differentiate indicating a developmental arrest." (PMID 29869612, 2018). "Additional studies have shown that depletion of JARID2 mRNA or inhibition of EZH2 led to increases in MYOG mRNA and differentiation-specific gene expression in rhabdomyosarcoma (RMS) cell lines." (PMID 30119689, 2018). "We observed that the rhabdomyosarcoma cell lines expressed their signature markers MYOD1 as well as downstream myogenic genes MYOGENIN and DESMIN." (PMID 30446688, 2018). "Small numbers of these cases were assigned provisional diagnoses, for example, rhabdomyosarcoma, if there was focal expression of appropriate markers (e.g., clear cut desmin with myogenin or MyoD1)." (PMID 25810689, 2015). "Negativity for myogenin and myoD1 expression is seen, and these markers differentiate synovial sarcomas from rhabdomyosarcomas." (PMID 26101678, 2015). "Muscle-specific markers such as desmin, myogenin, or myo-D1, characteristic of rhabdomyosarcoma, should be included in the immunohistochemical study." (PMID 25475214, 2014). "Commitment and maintenance of skeletal muscle differentiation during normal skeletal muscle myogenesis, as well as in Rhabdomyosarcoma, is regulated by a family of closely related genes (eg. myoD1, myogenin, myf-5, MRF-4), termed the MyoD family." (PMID 24455040, 2012). "MyoD1 and myogenin are considered useful markers in diagnosing Rhabdomyosarcomas and for differentiating it from other soft tissue tumors." (PMID 24455040, 2012). "For example, myogenin and myoD1 are specific and sensitive for the diagnosis of rhabdomyosarcoma and lymphoid markers such as CD20, CD3, CD30 and CD45 are very useful in the diagnosis of lymphoma." (PMID 20598147, 2010). "Contrarily, pediatric cases of sclerosing rhabdomyosarcoma expressed strong immunopositivity for all muscle markers, including MyoD1, Myogenin, Desmin and SMA, most likely reflecting a different stage of muscle maturity." (PMID 20701800, 2010). "Alveolar rhabdomyosarcoma exhibits a skeletal muscle differentiation which can be proven by immunohistochemical stains for skeletal-muscle specific markers (myogenin, Myo D1)." (PMID 18593459, 2008). "Myogenin, a potent marker for rhabdomyosarcoma, helped in exclusion of this tumors." (PMID 40158355, 2025). "In contrast, rhabdomyosarcomas express MyoD1 and myogenin, which help in differentiation." (PMID 41185734, 2025). "For myogenin, a transcription factor of myogenesis, its expression was absent in our case, and it has been reported to be specific to the pediatric malignancy, rhabdomyosarcoma." (PMID 41262926, 2025). "Immunohistochemistry showed positivity for rhabdomyosarcoma markers such as Desmin, MyoD1, and Myogenin in the rhabdomyosarcomatous component and positivity for neuroectodermal markers, including synaptophysin and chromogranin A in the neuroectodermal component." (PMID 41465905, 2025). "Myogenin, a potent marker for rhabdomyosarcoma, helped in exclusion of this tumor." (PMID 39921988, 2025). "In addition, DSFTs can exhibit aberrant immunophenotypes due to their heterogeneous differentiation, such as the presence of desmin and myogenin in the embryonal rhabdomyosarcoma component." (PMID 40432917, 2025).
rhabdomyosarcoma (continued). "In contrast, MyoD1 and myogenin demonstrate both high specificity and sensitivity for diagnosing RMS, with positive staining localized in the nucleus, making them reliable diagnostic markers for rhabdomyosarcoma." (PMID 40703554, 2025). "Desmin, myogenin, and MyoD1 help identify rhabdomyosarcoma components." (PMID 39450250, 2024). "After completing the histopathological examination, we established the diagnosis of IS and found areas of rhabdomyosarcoma differentiation microscopically, which was supported by the focal positivity of immunohistochemistry for MyoD1 and myogenin, which is rare in cardiac IS." (PMID 38835391, 2024). "Historically, rhabdomyosarcoma at our center has been more of a morphological diagnosis with further validation of diagnosis and or subtype by using immunohistochemical stains such as Desmin, Myogenin, and myoD1." (PMID 35942988, 2023). "Rhabdomyosarcoma can be distinguished from cervical NEC by the presence of myogenin and Myo-D1." (PMID 38025893, 2023). "The expression of PRMT1, CARM1, PRMT5, PRMT7, PRMT8 and PRMT9 were all elevated in rhabdomyosarcoma, CARM1 and its direct interaction with histone acetyltransferase PCAF jointly were also detected to exert an increased expression of myogenin gene and lead to rhabdomyosarcoma cell differentiation." (PMID 35311114, 2022). "Embryonal rhabdomyosarcomas use to be heterogeneous in their histological patterns; as well as the variable myogenin staining that they could show (ranging from 10% to 90% of tumor cells nuclei)." (PMID 36173721, 2022). "Moreover, SRF::NCOA2 fusion-positive pediatric RMS (rhabdomyosarcoma) showing diffuse staining for desmin and multifocal nuclear positivity for myogenin are reported." (PMID 36421692, 2022). "Rhabdomyosarcomas expressed vimentin, desmin, myoD1, and myogenin." (PMID 35001360, 2022). "Alveolar rhabdomyosarcomas are positive for Desmin, Myogenin, and Myo-D1." (PMID 34722090, 2021). "We identified 88 transcription factors, many of which have been described previously as part of the core regulatory transcription factor circuitry in specific cancer types, such as PHOX2B, TWIST1, and ISL1 in neuroblastoma; MYOD1 and MYOG in rhabdomyosarcoma; NR0B1 in Ewing sarcoma." (PMID 34818552, 2021). "Rhabdomyosarcoma may be diagnosed by the immunohistochemical or molecular detection of a myogenic regulatory factor, such as MyoD or myogenin." (PMID 28546788, 2017). "In those cases of ESFTs which display focal positivity for S100 or desmin, additional immunohistochemical stains for melanoma markers (HMB45, Melan-A) and specific skeletal muscle markers (myogenin, myoD1) can be utilized to exclude melanoma and rhabdomyosarcoma." (PMID 27413360, 2016). "Also the bland cellularity of the myxoma and the negativity for desmin and Myogenin speak against a botryoid-type embryonal (myxoid) rhabdomyosarcoma, of the head and neck in children." (PMID 27064694, 2016). "The noncartilaginous spindled tumor cells were negative for MyoD1, myogenin, and desmin by immunohistochemical staining (data not shown), thus excluding the possibility that the noncartilaginous component was a variant of rhabdomyosarcoma." (PMID 27248819, 2016). "Indeed, even amongst human studies of rhabdomyosarcoma enriched for the embryonal subtype, there exists conspicuous heterogeneity in the extent of myogenin expression." (PMID 25992772, 2015). "However, absence of myxoid stroma and inflammatory infiltrating, and nuclear immunoreactivity for myogenin and Myo-D1 are helpful to confirm the diagnosis of rhabdomyosarcoma." (PMID 26178751, 2015). "Expression of CD97, muscle actin, and myogenin in rhabdomyosarcomas of six patients." (PMID 24949957, 2014). "Myogenin, a rhabdomyosarcoma marker, allows this tumor to be excluded." (PMID 25027562, 2014).